ACSL1 (acyl-CoA synthetase long chain family member 1)
Diseases named in the same sentence as ACSL1 in open-access papers (continued):
Sharing a sentence is not in itself a finding about the gene and the disease.
tumor (continued). "In contrast, ACSL1 expression was remarkably reduced in RCC tumor cells compared to normal cells." (PMID 31089396, 2019). "An initial screening performed showed that 16 out of 70 lipid metabolism-related genes analyzed, including ACSL1, ACLS4 and SCD, might have a putative association with tumor aggressiveness." (PMID 26451612, 2015). "Notably, ACSL1 was downregulated in the tumor macrophage in our study." (PMID 36186437, 2022). "In summary, ACSL1 and ACSL4 are suspected to contribute to tumor progression in most of the tumor types examined, whereas ACSL5 appears to hinder tumor growth." (PMID 40932861, 2025). "ACSL1 and ACSL5 have prognostic significance in gliomas, influencing tumor immunity and immune cell migration, thereby providing valuable insights into low-grade glioma (LGG) prognosis and potential therapeutic targets." (PMID 41288931, 2025). "Consistently, a significant decrease in the mRNA levels of PPARa, ACLY, FASN, ACSL1 and ACSL5 was observed in the livers of C26 tumor-bearing mice compared with control mice." (PMID 38245529, 2024). "Concerning the 8 MRGs expression pattern, 4 genes, namely ACSL1, ALDH2, TP53AIP1, and ME3, were observed to be downregulated in tumor tissues while being upregulated in adjacent-normal tissues." (PMID 38310106, 2024). "Further investigation into the mechanism of the lipid-lowering effects of ECD revealed that it downregulated ACSL4, ACSL1, CPT1A, and FASN levels in colorectal tissues and downregulated tumor formation in the colorectum." (PMID 37078067, 2023). "More importantly, among the five family isoforms, ACSL1 and ACSL4 promote uncontrolled cell growth, facilitate tumor invasion, and lead to evasion of programmed cell death." (PMID 37078067, 2023). "Independent knockdown of ACSL1, ACSL3, or ACSL4 decreased cell proliferation and anchorage‐independent growth in many cancer cells and xenograft tumor growth in nude mice." (PMID 33030783, 2020). "Therefore, ACSL1 may be considered as a potential novel therapeutic target for tumor growth." (PMID 31581558, 2019). "This study broaden the prognostic value of ABCA1, ACSL1, AGPAT1 and SCD genes, independently of CRC tumor stage, leading to future precision medicine approaches and “omics”-guided therapies." (PMID 29464044, 2018). "In addition, a higher expression of ACSL1 and ACSL5 was significantly related to a low tumor grade (ACSL1, p = 0.023; ACSL5, p = 0.025), while a higher expression of ACSL4 was significantly associated with a high grade (p = 0.009)." (PMID 38539505, 2024). "The expression levels of ACSL1 and ACSF2 were higher in tumor tissues than in normal tissues." (PMID 39524444, 2024). "IHC demonstrated the upregulation of ACSF2, MTMR9, and CPNE3 in BRCA tissues, whereas ACSL1 expression was not significantly different between tumor tissues and adjacent tissues." (PMID 39524444, 2024). "Recent studies have shown that in HNSCC, the expression levels of the ACSL1 and TFRC genes are closely related to the occurrence of tumour cell ferroptosis and the prognosis of patients and are potential targets for the occurrence, development and treatment of HNSCC." (PMID 36600313, 2023). "We probed the mRNA and protein profiles of ACSL1 in RCC using data from the Cancer Genome Atlas, Gene Expression Omnibus, the Human Protein Atlas (HPA), and Clinical Proteomic Tumor Analysis Consortium (CPTAC) and verified them in our patient cohort and RCC cell lines." (PMID 37608295, 2023). "Moreover, we showed that BLCAP interacted with STAT3 and reduced STAT3 phosphorylation, overexpressed PRADX activated STAT3 phosphorylation, and promoted ACSL1 expression via suppressing BLCAP expression, accelerating tumor metabolism." (PMID 35574370, 2022). "Consistently, our data suggest that ACSL1 gene expression is upregulated by G0S2 ectopic expression in CML, and therefore may play a role in its tumour suppressor activity during CML disease progression and TKI response." (PMID 36536477, 2022).
tumor (continued). "Moreover, the combination of the ACSL1 and CPT1 inhibitors also reduced tumor growth both in vivo and in vitro." (PMID 35574370, 2022). "In contrast to tumor-enriched lipolysis and fatty acid synthesis enzymes that do not require oxygen, fatty acid metabolic genes that require molecular oxygen are depleted in the tumor region, including fatty acid desaturation (SCD, FADS2) and oxidation (ACSL1)." (PMID 32103057, 2020). "Overexpression of membranous FATP4 and CD36 combined with reduced cytoplasmic expression of ACSL1 might be a tumor-specific feature of RCC, contributing to the tumorigenesis and tumor progression." (PMID 31089396, 2019). "Meanwhile, RCC tumor cells showed remarkable increases in membranous FATP4 and CD36 and a decrease in ACSL1, indicating that RCC cells are metabolically different from normal cells and prefer the mechanism of fatty acid uptake from extracellular sources during tumorigenesis." (PMID 31089396, 2019). "For ACSL1, normal and RCC tumor cells showed diffuse cytoplasmic staining only." (PMID 31089396, 2019). "Importantly, high levels of ACSL1 and/or ACSL4 expression in patient tumor samples correlates with a worse prognosis." (PMID 31344914, 2019). "Of ACSLs, ACSL5 was considered as the target gene, although lysoPCs may stimulate ACSL isoform activations and promote isoform‐specific biological processes, for example, ACSL1‐involved pro‐inflammation, ACSL3‐regulated androgen responsiveness or ACSL4‐and ACSL5‐related tumour suppression." (PMID 36639836, 2023). "Finally, we determined that combined of ACSL1 and CPT1 inhibitors could reverse the accelerated cellular metabolism and tumor growth induced by PRADX overexpression in vivo and in vitro." (PMID 35574370, 2022). "However, unlike that of CD36 and FATP4, the staining intensity of ACSL1 was remarkably reduced in tumor tissues compared to normal cells." (PMID 31089396, 2019). "Real time PCR and Western blot analysis data showed that the expression of ACC1, but not ACSL1 and FASN was significantly increased in TDM, BMDM and in HCC tumor tissue with B. thetaiotaomicron or acetic acid treatment." (PMID 38270111, 2024). "Similarly, while the expression levels of ACLY, FASN, ACSL1, and ACSL5 in the liver tissues were decreased in C26 tumor-bearing mice compared with control mice without tumors, their expression levels were significantly increased in the liver tissues of the mice fed with a fenofibrate diet." (PMID 38245529, 2024).
cancer (50 papers, 2012 to 2026). A tumor composed of atypical neoplastic, often pleomorphic cells that invade other tissues. "ACSL1, associated with lipid metabolism, is an oncogene whose significance in many cancers is well established." (PMID 38419527, 2024). "Dysregulation of long-chain acyl-CoA synthetase 1 (ACSL1) is strongly implicated in undesirable results in varieties of cancers." (PMID 37608295, 2023). "In conclusion, ACSL1 is potentially a prognostic and diagnostic factor for ccRCC sufferers, and the variances in ACSL1 expression between ccRCC and other tumors may account for the different tumorigenesis mechanisms of ACSL1 in diverse cancer types." (PMID 37608295, 2023). "Thus, pharmacological inhibition of ACSL1 may provide promising therapeutic value in treating inflammatory-associated disorders such as cancer." (PMID 31847240, 2019). "Given the role of ACSL1 in carcinogenesis and the influence of genetic polymorphisms in regulation of gene expression and function, it is inferred that polymorphisms in this gene might exert an influence on cancer susceptibility and progression." (PMID 27992526, 2016). "Further, MCL‐1 regulates long‐chain fatty acid β‐oxidation in cancer cells through its interaction with Acyl‐CoA synthetase long‐chain family member 1 (ACSL1), an enzyme responsible for the conversion of free long‐chain fatty acids into fatty acyl‐CoA esters." (PMID 41420072, 2026). "Among these, PEBP1/STK11 co-expression strongly negatively correlates in all cancer types with enzymes that increase the biosynthesis of fatty acids such as members of the ACSL family (ACSL1, ACSL3, ACSL4, ACSL5, and ACSL6)." (PMID 40806276, 2025). "ACSL1 has also been identified as a potential target in cancer treatment, particularly due to its unique role of ACSL1 in immune-related factors, suggesting its value as a therapeutic target." (PMID 41288931, 2025). "In this study, we used TCGA data set to predicate the ACSL1 expression in various cancers and revealed that ACSL1 was down-regulated in 10 types of cancer, including ccRCC." (PMID 37608295, 2023). "In the TCGA database, pan-cancer analysis exhibited that the ACSL1 displayed differential expression with statistical significance in multiple cancers, like Kidney renal clear cell carcinoma (KIRC) and Kidney renal papillary cell carcinoma (KIRP)." (PMID 37608295, 2023). "ACSL4 has been previously reported overexpressed in malignant tumors, and together with ACSL1 and SCD form a metabolic axis involved in CRC progression." (PMID 31339921, 2019). "The negative-correlation of miR-205 and ACSL1 expression in hepatitis B virus X protein (HBx)-transgenic mice suggests that miR-205 leads to the dysregulation of lipid metabolism by ACSL1 and the cancer progression." (PMID 27171439, 2016). "Namely, Triacsin C (a potent inhibitor of ACS, including ACSL1) induce massive apoptosis and selective cytotoxicity in cancer cells." (PMID 25749516, 2015). "Notably, in the present study, ACSL1, ACSL5, and NUDT19 seemed to be cancer-promoting genes, as their upregulation was associated with poor survival." (PMID 38406287, 2024). "Furthermore, the elimination of ACSL1 also suppressed the ability to form cancer spheroids in OVCA429 and HM cells." (PMID 36882396, 2023). "This indicated that the level of ACSL1 in cancer cells could significantly modulate ferroptosis and cell growth." (PMID 36882396, 2023). "Importantly, the ACSL1 is deregulated in many tumors, leading to abnormal lipid synthesis and extracellular lipid uptake that promotes uncontrolled cancer cell proliferation." (PMID 35734439, 2022). "Several ACSLs-related reviews have summarized the mechanisms and function of the ACSLs in cancer: ACSL1 and ACSL3 may lead to cancer progression and worse prognosis, while ASCL5 and ACSL6 act as key suppressor with the opposite effect." (PMID 36507355, 2022). "Increasing studies support that ACSL1 is deregulated in clinical cancer." (PMID 34777393, 2021).
cancer (continued). "Thus, the inhibition of ACSL1/ACSL4/SCD axis by means of the selective effect of these drugs on cancer cells arises as a promising therapeutic strategy." (PMID 26451612, 2015). "Therefore, the current role of ACSL1 in cancer is still controversial." (PMID 39524444, 2024). "The high-throughput proteomics analysis revealed differential expressions of Acsl1, Plin1, Dbil5, Plin4, Col12a1, Col1a1, Col5a3, Col1a2, and Dcn, which are associated with the PPAR signaling pathway, protein digestion and absorption, and the protein glycan pathway in cancer." (PMID 36874004, 2023). "Therefore, ACSL1 might be a reflection of M1 macrophages, and M2 macrophages might be more prevalent in cancer tissues, especially in TNBC." (PMID 36186437, 2022). "Therefore, targeting ACSL1 may be a new therapeutic strategy to prevent the inflammatory processes involved in cancer metastasis." (PMID 31581558, 2019). "Inhibition of MCL-1 results in decreased oxidation of long-chain fatty acids (LCFAs) in cancer cells, likely due to the disrupted interaction between MCL-1 and the BH3-like domain of acyl-CoA synthetase long-chain family member 1 (ACSL-1)." (PMID 41427398, 2025). "PPAR signaling pathway has been previously reported to be regulated by NAT10 through ac4C modification of genes such as ELOVL6, ACSL1, ACSL3, ACSL4, ACADSB, and ACAT1, thus modulating fatty acid metabolism in cancer cells." (PMID 40123006, 2025). "Recent studies have identified crucial roles of ACSL1, ACSL3, and ACSL4 in ferroptosis, thereby opening new avenues for exploring their involvement in tumorigenesis and cancer therapy." (PMID 41288931, 2025). "Along with ACSL4 and ACSL1, ACSL5 has also been considered an immune-dependent cancer suppressor gene." (PMID 41288931, 2025). "Therefore, ACSL1 may play an oncogenetic role in different cancer types." (PMID 38406287, 2024). "To address the role of ACSL1 in controlling protein degradation of FSP1, we found that ACSL1 participated in protein N-myristoylation by increasing myristic acid levels in cancer cells." (PMID 36882396, 2023). "RNA‐seq data from our study showed decreased expression of ACSL1, ACSL3 and ACSL4 in NAT10‐depleted cancer cells, which further confirmed that the mRNA transcripts of these genes are controlled by NAT10‐dependent ac4C mRNA acetylation." (PMID 36149760, 2022). "The results showed that certain genes (such as GPX4, SLC7A11 and GSS) displayed higher expression, while others (such as ACSL1 and ACSL4) displayed lower expression in some cancer types." (PMID 34975326, 2022). "Thus, ACSL1 may have an important role in cancer and the innate immune response." (PMID 34777393, 2021). "We also found a number of genes whose expression follows this pattern: high-grade cancers < low-grade cancers < normal tissue, such as ALDH1L1, WIF1, ACSL1, FOS, and ABLIM1 in at least four cancer types." (PMID 28427185, 2017). "It is interesting to note that PTPRE is coexpressed with ACSL1 and ACSL5 in cancer, which warrants further investigation." (PMID 27171439, 2016). "On the other hand, ACSL1 is an isozyme of Acyl-CoA synthetase (ACS) family, known to play an important role in lipid metabolism, cancer cell survival and apoptosis inhibition." (PMID 25749516, 2015). "The robust protumor action of ACSL1/ACSL4/SCD network, together with the fact that all three of them are lipid metabolism enzymes, makes these druggable proteins attractive targets for cancer therapy." (PMID 26451612, 2015). "Further investigation is required to determine whether ACSL1 localization is affected by MCL inhibition in hNSCs, as reported in cancer cells." (PMID 41427398, 2025). "In addition to ACSL1, ACSL4, and ACSL5, ACSL3 and ACSL6 also contribute to cancer progression, with their roles to be further elaborated in the context of specific cancers." (PMID 41288931, 2025).
cancer (continued). "However, despite extensive research on PRICKLE3, TNFSF10, ACSL1 and EP300 in relation to cancer, immunity, and metastasis, their precise involvement in primary resistance mechanisms in SCLC remains unclear and requires further study." (PMID 38957470, 2024). "Thus, the role of ACSL1, carbonic anhydrase, and SCD1 in cancer are all supported by literature." (PMID 32103057, 2020). "Additionally, other non-cancer drugs may be repurposed for targeting ACS in cancer cells, such as aspirin, which was found to suppress the abnormal lipid metabolism of HCC cells through inhibiting acyl-CoA synthetase long-chain family member 1 (ACSL1)." (PMID 35448537, 2022). "Correspondingly, ACSL1 overexpression but not ACSL4 stimulated N-cadherin or Slug expression, well-known EMT markers involved in cancer invasion and metastasis." (PMID 28894242, 2017).
infection (23 papers, 2012 to 2025). The state of being infected such as from the introduction of a foreign agent such as serum, vaccine, antigenic substance or organism. "In this study, WB analysis revealed a decrease in ACSL1 protein levels following infection but an increase after NAM treatment." (PMID 38971783, 2024). "The wild-type proteins (ACSL1-WT) and mutant (ACSL1-MT) were stably overexpressed by lentivirus infection in NM cells, OVCA429 cells, and HM cells, respectively." (PMID 36882396, 2023). "Accordingly, ACSL1 inhibitor Triacsin C suppressed MHV-A59-infection-induced syncytia formation and viral propagation in primary macrophages." (PMID 34960652, 2021). "Expectedly, upon ALV-J infection, mRNA levels of ACSL1 in MDMs were significantly decreased by 24 h post-infection (hpi)." (PMID 34777393, 2021). "We first determined the effects of ACSL1 inhibitor Triacsin C on MHV-A59 infection in murine macrophages." (PMID 34960652, 2021). "At the gene level, expression of RAB8B, ACSL1 and Dynamin-1 was minimum in case of uninfected macrophages, intermediate in case of H37Ra infection and highest in the case of H37Rv infection." (PMID 28257432, 2017). "Of note, the genes that facilitate FM generation like Acsl1, Adrp, Psap and Fat exhibited elevated expression on infection with mycobacteria." (PMID 27532872, 2016). "In the present study, we analyzed different time points of infection and found that ACSL1, ACSL3, ACSL4, ACSL5 and ACSL6 were all recruited into the lumen of the Ct inclusion as early as 6 hpi and as late as 24 hpi." (PMID 26988341, 2016). "For ferroptosis, the significantly up-regulated proteins shared by the L. monocytogenes 10403s and M7 infection groups were Acsl5, Tf, Acsl1, Tfrc, and Lpcat3, and the significantly down-regulated proteins were Fth1 and Ftl1: neither changed significantly in the comparison group." (PMID 35682909, 2022). "To verify this hypothesis, we first overexpressed ACSL1 in DF-1 cells prior to infection with ALV-J and then performed immunoblot assays." (PMID 34777393, 2021). "ACSL1 inhibitor Triacsin C efficiently suppressed MHV-A59 infection." (PMID 34960652, 2021). "In addition, the anchorage-independent growth and cell migration were inhibited in HCT116 after lentiviral particles expressing ACSL1 shRNA infection." (PMID 27171439, 2016). "Based on the results above, we suspected that targeting ACSL1 may help eliminate MHV-A59 infection." (PMID 34960652, 2021). "Both inhibition of ACSL1 with Triacsin C, and inhibition of ferroptosis, protected cells from MHV-A59 infection." (PMID 34960652, 2021). "The results showed that upon infection, the levels of ATP and JC1 were decreased in MDMs overexpressing ACSL1, while were increased in ACSL1 knockdown cells." (PMID 34777393, 2021). "The pattern of splicing of genes IL1B, ACSL1 and ATG13 upon infection with H37Ra or H37Rv followed the trend observed in THP-1 macrophages, showing maximum expression in H37Rv infected cells than others." (PMID 28257432, 2017). "Moreover, genes involved in active metabolism like COX7A2, NDUFB6 (ILC2), NDUFA12 (ILCP), ACSL1 (NK CD16high), and DNAJA4 (NK CD56high) were upregulated in HIV-infected children, suggesting active metabolism in these subsets in response to infection." (PMID 32937142, 2020). "In macrophages derived from peripheral blood of healthy donors (MDMs), we could confirm infection specific alterations in the expression of IL1B, ACSL1, ATG13 and RAB8B isoforms as noted in THP-1 macrophages." (PMID 28257432, 2017). "The siRNA screen and RNA expression analysis revealed roles for a subset of long chain acyl-CoA synthetases following infection: SLC27A6 and ACSL1 were both siRNA hits and increased at the mRNA level, and SLC27A3 was an siRNA hit but not increased in mRNA abundance." (PMID 23696731, 2013). "We detected some significantly upregulated proteins upon infection: IRG1, GBP5, ICAM1, ACSL1, and PDL1 independently on the presence or absence of SLAMF1." (PMID 39000601, 2024).
immune diseases (3 papers, 2020 to 2023). "RNA-seq showed that overexpression of ACSL1 causes some changes in genes involved in the immune pathway, suggesting that the ACSL1 gene may play an important role in some immune diseases such as lipid metabolism-related diseases and thus requires further investigation." (PMID 32192050, 2020).
kidney disease (3 papers, 2019 to 2025). "Animal models have demonstrated that ACSL1 modulates lipid metabolism, inflammation, and oxidative stress in kidney disease." (PMID 40034430, 2025).